URGCP (upregulator of cell proliferation)
Description:
May be involved in cell cycle progression through the regulation of cyclin D1 expression. May participate in the development of hepatocellular carcinoma (HCC) by promoting hepatocellular growth and survival. May play an important role in development of gastric cancer.
Synonyms: KIAA1507; URG4; FLJ20654; DKFZp666G166; DKFZp686O0457
Tractability: PROTAC: ubiquitination databases record sites on it; its protein half-life has been measured.
Gene: Protein-coding gene on chromosome 7 (43,875,894 to 43,926,411, reverse strand). Ensembl gene ENSG00000106608.
Subcellular location: Cytoplasm; Nucleus
Subcellular location (Human Protein Atlas): Cytosol
Gene Ontology:
Molecular function: GTP binding
Cellular component: cytoplasm; cytosol; nucleus
Genetic constraint (gnomAD): Loss-of-function variants: 16 observed, 37.16 expected, observed/expected ratio (o/e) 0.43, 90% interval 0.29 to 0.65. The upper end of that interval is the gene's LOEUF score, 0.65, which puts it in group 2 of 6, group 1 being the genes least tolerant of losing a copy. Missense variants: 896 observed, 1,240.3 expected, observed/expected ratio (o/e) 0.72, 90% interval 0.68 to 0.76. Synonymous variants: 443 observed, 504.88 expected, observed/expected ratio (o/e) 0.88, 90% interval 0.81 to 0.95.
Homologues: Orthologues: chimpanzee URGCP (100% identical), macaque URGCP (98% identical), guinea pig URGCP (88% identical), dog URGCP (87% identical), pig URGCP (86% identical), rat Urgcp (86% identical), mouse Urgcp (83% identical), tropical clawed frog urgcp (38% identical), zebrafish si:dkey-85k7.12 (36% identical), zebrafish si:dkey-204a24.11 (33% identical), zebrafish urgcp (32% identical), zebrafish gvin1l2 (23% identical).
Diseases named in the same sentence as URGCP in open-access papers:
URGCP is named in the same sentence as 29 diseases in open-access papers, as found by Europe PMC text mining. Sharing a sentence is not in itself a finding about the gene and the disease. The quoted sentences say what the papers report.
hepatocellular carcinoma (10 papers, 2012 to 2023). A malignant tumor that arises from hepatocytes. "The underlying mechanism of URGCP-induced NF-κB pathway activity in glioma cells still unclear, while, some reports indicate that URGCP increases the levels of phosphorylated IKKs in hepatocellular carcinoma cells and non-small cell lung cancer cells." (PMID 29044221, 2017). "Experimental and clinical evidence points to a strong expression of URGCP in multiple cancers, including hepatocellular carcinoma, gastric cancer, osteosarcoma, and epithelial ovarian cancer." (PMID 29044221, 2017). "Furthermore, multiple findings have confirmed that URGCP supports sustained in vivo and in vitro growth of hepatocellular carcinoma by inducing a decrease in p27Kip1 and p21Cip1 levels and an increase in Cyclin D1 expression." (PMID 29044221, 2017). "URGCP/URG4 is associated with poor prognosis in hepatocellular carcinoma and its overexpression increased cellular entry into the G1/S transitional phase in hepatocellular carcinoma cells." (PMID 27443843, 2016). "URGCP, known as URG 4, is upregulated in many common cancers, including hepatocellular carcinoma, osteosarcoma, epithelial ovarian cancer, and GC 46-49." (PMID 33854599, 2021). "Up-regulator of cell proliferation (URGCP/URG4), first identified as one of eight genes upregulated by HBxAg transduction in HepG2 cells, is highly expressed in HBV-infected liver cells and hepatocellular carcinoma (HCC) cells." (PMID 26429875, 2015). "In hepatocellular carcinoma (HCC), URGCP/URG4 may be considered as a natural effector of hepatitis Bx antigen (HBxAg) which contributes to hepatocarcinogenesis, URGCP/URG4 is up-regulated in the presence of HBxAg." (PMID 26429874, 2015).
gastric cancer (7 papers, 2012 to 2023). A primary or metastatic malignant neoplasm involving the stomach. "URGCP also plays an important role in the proliferation of gastric cancer cells by upregulating Cyclin D1 expression." (PMID 26429875, 2015). "URGCP/URG4 is upregulated in human gastric cancer tissues and cell lines, and overexpression of URGCP/URG4 promotes gastric cancer cells proliferation and tumorigenicity." (PMID 26429874, 2015). "URGCP expression is upregulated in various types of human cancer, including HCC, gastric cancer, epithelial ovarian cancer and osteosarcoma." (PMID 26429875, 2015). "Besides the hepatocarcinogenesis function of URG4/URGCP, it has been reported that URG4/URGCP is also upregulated in gastric cancer tissues and cells and enhances gastric cancer cell proliferation and tumorigenesis." (PMID 25947641, 2015). "Previous studies demonstrated that URG4/URGCP is upregulated in human HCC and gastric cancer and URG4/URGCP could promote the proliferation and tumorigenicity of HCC and gastric cancer cells." (PMID 25947641, 2015). "Furthermore, it has been shown that overexpression of URGCP/URG4 in HCC and gastric cancer cells upregulated cyclin D1, whereas repression of URGCP/URG4 downregulated it." (PMID 22815774, 2012). "Overexpression of URGCP/URG4 in HCC and gastric cancer cells was found to promote cell growth and survival in tissue culture and soft agar; however, the in vivo effect of URGCP/URG4 on HCC remains unknown." (PMID 22815774, 2012).
osteosarcoma (7 papers, 2012 to 2023). A usually aggressive malignant bone-forming mesenchymal neoplasm, predominantly affecting adolescents and young adults. "Moreover, URGCP/URG4 can function as a proto-oncogene and is associated with tumor metastasis and recurrence in osteosarcoma." (PMID 26429874, 2015). "Moreover, overexpressed URGCP/URG4 in osteosarcoma tissues has been linked to tumor recurrence and metastasis, as well as the proliferative activity of osteosarcoma cells, suggesting that URGCP/URG4 may be a valuable prognostic marker for certain types of human cancer." (PMID 22815774, 2012). "In osteosarcoma, LINC00514 increases URGCP expression to promote cell cycle and suppress cell apoptosis via sponging miR-708." (PMID 33757509, 2021). "The clinical significance of URGCP upregulation with higher clinical staging and shorter overall survival has been suggested in patients with HCC, ovarian cancer and osteosarcoma." (PMID 26429875, 2015).
bladder cancer (2 papers, 2015 to 2023). "we investigated the correlation between URGCP/URG4 expression and the patients’ clinicopathplogic characteristics used 127 paraffin-embedded, archival bladder cancer tissues." (PMID 26429874, 2015). "Taken together, these results demonstrated that URGCP/URG4 inhibits cisplatin-induced apoptosis of bladder cancer cells in vivo." (PMID 26429874, 2015). "Taken together, our results suggested that knockdown of URGCP/URG4 impaired the ability of bladder cancer cells to resist cell death induced by cisplatin." (PMID 26429874, 2015). "We also analyzed the correlation between URGCP/URG4 expression and clinical parameters, and found URGCP/URG4 expression was correlated with bladder cancer progression, it was an unfavorable factor for patient's survival." (PMID 26429874, 2015). "In summary, URGCP/URG4 promotes the resistance to cisplatin-induced apoptosis by activating NF-κB pathway, and is an unfavorable prognostic factor for bladder cancer." (PMID 26429874, 2015). "Consistently, inhibition of URGCP/URG4 enhanced cisplatin-induced apoptosis of bladder cancer cells, for which tumor sizes were much smaller." (PMID 26429874, 2015). "Here, we first determined URGCP/URG4 expression in bladder cancer cells and tissues, then we studied the effect of URGCP/URG4 on anti-apoptotic effect by modulating its expression both in vitro and in vivo." (PMID 26429874, 2015). "These suggested the expression of URGCP/URG4 is correlated with the prognosis of bladder cancer significantly." (PMID 26429874, 2015). "In summary, we found URGCP/URG4 was high expression in bladder cancer cells and tissues, it promoted the resistance to cisplatin-induced cell apoptosis in bladder cancer, mechanism analysis found it activated NF-κB pathway to inhibit apoptosis." (PMID 26429874, 2015). "We also analyzed the correlation between URGCP/URG4 expression and clinical clinicopathologic, and found its expression was positively correlated with bladder cancer progression, it can serve as a valuable prognostic factor." (PMID 26429874, 2015). "Ectopic expression of URGCP/URG4 promoted the resistance to cisplatin-induced cell apoptosis in bladder cancer, while silencing expression of URGCP/URG4 enhanced the cisplatin-induced apoptosis, both in vitro and in vivo." (PMID 26429874, 2015). "All the results revealed that URGCP/URG4 promotes the resistance to cisplatin-induce apoptosis in bladder cancer cells via activation of NF-κB signaling pathway." (PMID 26429874, 2015). "After treated with cisplatin, the volume and weight of URGCP/URG4-overexpressing tumors were markedly higher compared to the tumors formed by control cells, indicating the anti-apoptosis function of URGCP/URG4 on bladder cancer cells in vivo." (PMID 26429874, 2015). "These suggested that URGCP/URG4 is upregulated in bladder cancer, indicating a putative correlation with bladder cancer progression." (PMID 26429874, 2015). "All the results revealed that ectopic URGCP/URG4 inhibited cisplatin-induced apoptosis, it might play critical role in bladder cancer progression and therapy." (PMID 26429874, 2015). "these suggested high URGCP/URG4 expression in primary bladder cancer patients with poor survival." (PMID 26429874, 2015). "Cancer stem cell plays critical role in drug resistance, whether URGCP/URG4 could regulate bladder cancer stem cell still needed to be investigated." (PMID 26429874, 2015). "We found URGCP/URG4 expression was a independent prognostic factor for bladder cancer patients." (PMID 26429874, 2015). "In our study, we demonstrated that URGCP/URG4 was upregulated in bladder cancer cells and tissues." (PMID 26429874, 2015). "Meanwhile, we used eight fresh bladder cancer tissues and one normal bladder tissue to investigate URGCP/URG4 expression, and found URGCP/URG4 expression was upregulated in most of bladder cancer tissues (indicated as T) compared to that of in normal tissue (indicated as N)." (PMID 26429874, 2015).
bladder cancer (continued). "The correlation analysis between URGCP/URG4 expression and clinicopathologic parameters suggested URGCP/URG4 expression was correlated with the progression of bladder cancer, and was an unfavorable prognostic factor." (PMID 26429874, 2015). "qRT-PCR analysis found the expression of NF-κB-targeted genes, including CCND1, Bcl-2, MMP9 and VEGF were upregulated once overexpression of URGCP/URG4, whereas knockdown of URGCP/URG4 significantly inhibited the levels of these genes in bladder cancer cells." (PMID 26429874, 2015). "In our study, we determined that URGCP/URG4 overexpression promoted the resistance to cisplatin-induced bladder cancer cells apoptosis, indicating its function and potential utilization in bladder cancer chemotherapeutic treatment." (PMID 26429874, 2015). "However, the role of URGCP/URG4 in bladder cancer has not been elucidated." (PMID 26429874, 2015).
neuroblastoma (2 papers, 2022 to 2023). Neuroblastoma (NB) is the most common solid, extracranial childhood tumor. "VPA also inhibited the proliferation of SHSY5Y neuroblastoma (NB) cancer cells in a time- and dose-dependent manner by downregulating URG4/URGCP and its transcriptional target CCND1, leading, in turn, to cell cycle arrest." (PMID 36139561, 2022).
glioma (1 paper, 2017). A benign or malignant brain and spinal cord tumor that arises from glial cells (astrocytes, oligodendrocytes, ependymal cells). "One study has identified that URGCP is expressed at high levels in gliomas, which acts as a potential diagnostic biomarker and immunotherapeutic target for glioma patients." (PMID 29044221, 2017). "Notably, URGCP has been indentified to act as a potential diagnostic biomarker and immunotherapeutic target for glioma patients." (PMID 29044221, 2017). "Western blotting and RT-qPCR assays also showed that both the protein and mRNA expression levels of URGCP were significantly upregulated in glioma tissues, compared to that of normal brain tissues." (PMID 29044221, 2017). "To investigate the role of miR-16 in glioma growth in vitro, we transfected anta-miR-16 into shURGCP-U87 and shURGCP-U251 cells, EdU labeling showed that anta-miR-16 recovered the proliferation activity of URGCP-silenced glioma cells in vitro." (PMID 29044221, 2017). "We found that the levels of URGCP were upregulated in glioma, and that the high-levels of URGCP indicated a worse prognosis in glioma patients." (PMID 29044221, 2017). "Next, we examined the expression levels of URGCP in glioma cell lines, western blotting revealed that the protein levels of URGCP were markedly higher in U87, U251, A172 and primary glioma cells, compared to primary astrocytes." (PMID 29044221, 2017). "This study also provides the first demonstration that URGCP is a positive regulator of tumor growth in glioma, while, knockdown of URGCP effectively suppresses cell proliferative activity and tumor growth via inhibiting the G1/S transition." (PMID 29044221, 2017). "Taken together, these data suggest that the expression levels of URGCP are widely upregulated in glioma." (PMID 29044221, 2017). "To investigate the biological significance of URGCP in glioma, we first silenced URGCP in U87 cells by small interfering RNA (siRNA)." (PMID 29044221, 2017). "And, more remarkable, URGCP also regulated the mRNA levels of Cyclin D1 and Cyclin E1 in glioma, suggesting that the transcriptional regulation is involved in this process, and the underlying mechanisms need further investigation." (PMID 29044221, 2017). "In this study we tried to investigate the oncogenic roles and molecular mechanisms of URGCP in glioma." (PMID 29044221, 2017). "Next, to evaluate the effects of URGCP on glioma growth in vivo, we first established URGCP stably silenced U87 cells by short hairpin RNA (shRNA)." (PMID 29044221, 2017). "Importantly, these results also suggest that NF-κB pathway is critical for URGCP-induced Cyclin D1 and Cyclin E1 expression in glioma." (PMID 29044221, 2017). "Mechanically, URGCP repressed miR-16 expression via activating NF-κB/c-myc pathway in glioma; Cyclins D1 and Cyclin E1 were identified as the direct targets of miR-16, thus, URGCP-mediated miR-16 downregulation accelerated cell proliferation by upregulating Cyclin D1 and Cyclin E1 expression." (PMID 29044221, 2017). "URGCP and miR-16 are critical for glioma growth: silencing URGCP (shURGCP) inhibited glioma growth, while, the shURGCP-mediated proliferative inhibition could be recovered by antagonizing miR-16 (anta-miR-16) in vivo and in vitro." (PMID 29044221, 2017). "However, the bio-functions and molecular mechanisms of URGCP in the progression of glioma warrant further investigation." (PMID 29044221, 2017). "Second, to test whether URGCP regulates miR-16 expression in glioma, we silenced URGCP and found that silencing URGCP enhanced miR-16 expression in U87 and U251 cells." (PMID 29044221, 2017). "The significance of URGCP to these clinical features suggests that URGCP may be helpful for predicting the prognosis of patients with glioma." (PMID 29044221, 2017). "To investigate whether NF-κB pathway is involved in URGCP-increased Cyclin D1 and Cyclin E1 expression in glioma, we performed western blotting." (PMID 29044221, 2017).
glioma (continued). "In this study, we demonstrated that URGCP-mediated nuclear translocation of NF-κB/p65 induces c-myc expression, suggesting that the activation of NF-κB pathway is involved in URGCP-mediated c-myc unregulation in glioma." (PMID 29044221, 2017). "Indeed, we found positive correlations between URGCP and Cyclin D1 and Cyclin E1 expression in glioma tissues." (PMID 29044221, 2017). "Here, our study indicates that URGCP promotes glioma growth through upregulating Cyclin D1 and Cyclin E1 expression, and the NF-κB/c-myc/miR-16 pathway is involved in URGCP-mediated Cyclin D1 and Cyclin E1 overexpression in glioma." (PMID 29044221, 2017). "We found that overexpressing URGCP suppressed miR-16 expression, while, silencing URGCP significantly upregulated miR-16 expression in U87 and U251 cells, suggesting that the low-levels of miR-16 expression is maintained at least in part by URGCP in glioma." (PMID 29044221, 2017). "Finally, to visualize the subcell location of URGCP in glioma cells, immunofluorescence staining was performed." (PMID 29044221, 2017). "To test the correlations between URGCP and Cyclin D1 and Cyclin E1 expression in glioma, we first performed western blotting and found that the levels of Cyclin D1 and Cyclin E1 protein were upregulated in glioma tissues compared to normal tissues." (PMID 29044221, 2017). "To investigate whether URGCP regulates the expression of these regulators in glioma, we performed western blotting and found that silencing URGCP only suppressed Cyclin D1 and Cyclin E1 expression, while, URGCP overexpression enhanced Cyclin D1 and Cyclin E1 expression in U87 and U251 cells." (PMID 29044221, 2017). "All these results suggested that URGCP accelerates glioma growth through the NF-κB/c-myc/miR-16/Cyclin D1/E1 pathway, and both URGCP and miR-16 function as a novel cell cycle regulators in glioma and could be considered as potential targets for glioma therapy." (PMID 29044221, 2017). "However, the oncogenic role of URGCP in glioma still remains elusive." (PMID 29044221, 2017). "Therefore, we asked whether miR-16 is involved in URGCP-induced Cyclin D1 and Cyclin E1 expression in glioma." (PMID 29044221, 2017). "In addition to identifying a new mechanism of action for URGCP in glioma, our results also suggest that URGCP and miR-16 may be considered as candidates for targeted glioma treatment." (PMID 29044221, 2017). "Consistent with these well-studied processes, our study demonstrated that URGCP upregulates the level of p-IκBα and promotes the nuclear translocation of NF-κB/p65 in glioma cells, suggesting that the NF-κB pathway plays an essential role in the URGCP-induced glioma cell proliferation." (PMID 29044221, 2017). "In addition, we identified Cyclin D1 and Cyclin E1 as direct targets of miR-16 in glioma cells, overexpressing miR-16 significantly decreased Cyclin D1 and Cyclin E1 expression in glioma cells, suggesting that miR-16 is involved in URGCP-enhanced Cyclin D1 and Cyclin E1 expression in glioma." (PMID 29044221, 2017). "Despite the undeniable role of URGCP in tumor progression, the bio-functions of URGCP and URGCP-mediated miRNAs have not been explored in glioma." (PMID 29044221, 2017). "URGCP immunostaining was only slightly detectable in non-tumoral brain tissue but were differentially upregulated in glioma tissues at distinct clinical stages." (PMID 29044221, 2017). "The expression level of URGCP was markedly higher in orthotopic glioma compared to non-tumoral brain tissue." (PMID 29044221, 2017). "In this study, we detected URGCP expression in glioma specimens and showed that high-levels of URGCP positive correlated with the clinical stages of glioma, while, negative correlated with the overall survival time of glioma patients." (PMID 29044221, 2017). "In addition, we also found a negative correlation between URGCP and miR-16 expression in glioma tissues." (PMID 29044221, 2017).
glioma (continued). "However, at present, no work has assessed the relationship between URGCP and miRNAs in glioma." (PMID 29044221, 2017). "However, the exact Biological effects of URGCP in glioma have not been precisely characterized." (PMID 29044221, 2017).
metastatic disease (1 paper, 2015). "Collectively, these findings provide new insights into the potential role of URGCP upregulation in promoting NSCLC invasion and metastasis and suggest a potential to inhibit URGCP for NSCLC patients with metastatic disease." (PMID 26429875, 2015).